GRAMD2A (GRAM domain containing 2A)
Description:
Participates in the organization of endoplasmic reticulum-plasma membrane contact sites (EPCS) with pleiotropic functions including STIM1 recruitment and calcium homeostasis. Constitutive tether that co-localize with ESYT2/3 tethers at endoplasmic reticulum-plasma membrane contact sites in a phosphatidylinositol lipid-dependent manner. Pre-marks the subset of phosphtidylinositol 4,5-biphosphate (PI(4,5)P2)-enriched EPCS destined for the store operated calcium entry pathway (SOCE).
Synonyms: GRAMD2
Tractability: Antibody: UniProt places it where antibodies can reach, with high confidence; its Gene Ontology location is reachable by antibodies, with high confidence; UniProt predicts a signal peptide or a membrane-spanning region.
Gene: Protein-coding gene on chromosome 15 (72,159,806 to 72,197,830, reverse strand). Ensembl gene ENSG00000175318.
Subcellular location: Endoplasmic reticulum membrane; Cell membrane
Subcellular location (Human Protein Atlas): Nuclear speckles; Nucleoli; Cytosol
Gene Ontology:
Molecular function: endoplasmic reticulum-plasma membrane adaptor activity; phosphatidylinositol binding; phosphatidylinositol-4,5-bisphosphate binding; protein binding
Biological process: regulation of store-operated calcium entry
Cellular component: endoplasmic reticulum membrane; organelle membrane contact site; plasma membrane; cytoplasm
Genetic constraint (gnomAD): Loss-of-function variants: 32 observed, 46.09 expected, observed/expected ratio (o/e) 0.69, 90% interval 0.52 to 0.93. The upper end of that interval is the gene's LOEUF score, 0.93, which puts it in group 3 of 6, group 1 being the genes least tolerant of losing a copy. Missense variants: 411 observed, 430.74 expected, observed/expected ratio (o/e) 0.95, 90% interval 0.88 to 1.03. Synonymous variants: 136 observed, 160.97 expected, observed/expected ratio (o/e) 0.84, 90% interval 0.73 to 0.97.
Homologues: Orthologues: chimpanzee GRAMD2A (98% identical), macaque GRAMD2A (90% identical), dog GRAMD2A (70% identical), mouse Gramd2a (68% identical), rat Gramd2a (66% identical), guinea pig GRAMD2A (65% identical), rabbit GRAMD2A (62% identical), zebrafish gramd2aa (43% identical), Drosophila melanogaster GramD1B (21% identical), Caenorhabditis elegans ZC328.3 (14% identical). Paralogues in human: GRAMD2B (30% identical), GRAMD1A (24% identical), GRAMD1B (22% identical), GRAMD1C (19% identical).
Diseases named in the same sentence as GRAMD2A in open-access papers:
GRAMD2A is named in the same sentence as 1 disease in open-access papers, as found by Europe PMC text mining. Sharing a sentence is not in itself a finding about the gene and the disease.
GRAMD2A shares sentences with these, for which no sentence is quoted: cancer (1 paper).